MIF (macrophage migration inhibitory factor)
Diseases named in the same sentence as MIF in open-access papers (continued):
Sharing a sentence is not in itself a finding about the gene and the disease.
COVID-19 (26 papers, 2021 to 2025). A disease caused by infection with severe acute respiratory syndrome coronavirus 2. "Both receptors mediate differential MIF responses related to immune cell infiltration and have been implicated in COVID-19 and acute lung injury." (PMID 41152229, 2025). "Another study on 36 mechanically ventilated COVID-19 patients revealed that elevated MIF levels were associated with organ dysfunction and lower survival rates." (PMID 37568438, 2023). "A polymorphism analysis of MIF promoter alleles revealed an association between COVID-19 progression and the enhanced expression of a distinct allele of this molecule in patients." (PMID 37946732, 2023). "Overall, these studies suggest that MIF plays a crucial role in predicting disease severity and outcome in COVID-19 patients, aiding in early risk assessment and personalized treatment strategies." (PMID 37568438, 2023). "We speculate that the observed upregulation of CD74 reflects increased COVID-19-induced T-cell activation states, which might enhance susceptibility towards MIF." (PMID 38992165, 2024). "Furthermore, patients with COVID-19 exhibited lower frequency of the high-expression MIF CATT7 allele compared to healthy controls, but inpatients had a higher frequency of this allele than outpatients." (PMID 37568438, 2023). "Thus, these two pathogenic factors in COVID-19, MIF and activated bystander CD8+ T cells may have simultaneously effects on disease progression and lethality." (PMID 37946732, 2023). "Given the fact that fatal COVID-19 infections might be associated with an uncontrolled cytokine storm and given MIF’s upstream role in innate immunity and inflammation, we hypothesized that increased MIF levels might be associated with poor outcome and survival of COVID-19 patients." (PMID 33671433, 2021). "COVID-19 patients under PTIC treatment showed a significant decrease in Mo1 percentages and cytokines (IP-10/MIF/eotaxin/IL-8/IL-1RA/M-CSF) associated with STAT1 and an increase in the Mo2 subset." (PMID 39940787, 2025). "In a manner similar to MIF, the D-DT transcripts were also significantly augmented as compared to healthy controls in COVID-19 patients with moderate diseases, while only a trend toward upregulation was observed in patients with severe disease." (PMID 37568438, 2023). "Our analysis of the transcriptomic dataset GSE152418 showed a significant increase in MIF levels in PBMCs from COVID-19 patients with moderate and severe disease, as compared to healthy donors’ PBMCs." (PMID 37568438, 2023). "Previous studies have already explored the role of MIF in COVID-19, and we aimed at building upon those observations in order to provide a more comprehensive understanding of the role of the MIF pathway in COVID-19." (PMID 37568438, 2023). "Our analysis revealed a significant increase in MIF levels in both moderate and severe cases of COVID-19, as compared to PBMCs collected from healthy donors." (PMID 37568438, 2023). "COVID-19 patients showed high MIF plasma levels and the expression of MIF receptor molecules on T cells." (PMID 37946732, 2023). "Our results showed a significant increase in MIF levels in PBMCs from COVID-19 patients, as well as a significant increase in the D-DT levels in PBMCs." (PMID 37568438, 2023). "In different inflammatory diseases of lung, levels of circulating MIF are elevated, raising the intriguing question if this molecule is involved in the pathogenesis of COVID-19 and/or Long-COVID." (PMID 37946732, 2023). "This expression can make T lymphocytes more susceptible to MIF signaling and to CD74-dependent activation, since also the signaling coreceptor molecules CXCR2 and CXCR4 were enhanced on T cells in COVID-19 patients." (PMID 37946732, 2023). "In our study, we characterized CD4+ and CD8+ T cells for their expression of receptors recognizing MIF in order to define the role of this soluble mediator in COVID-19 immunopathology and determine the interplay between these two pathogenic mechanisms." (PMID 37946732, 2023).
COVID-19 (continued). "The receiver operating characteristic (ROC) analysis demonstrated that the following chemokines: MIP-1α, IP-10, and MIG, and the following GFs: basic-FGF, HGF, SCGF-β, G- CSF, M-CSF, and MIF can be useful parameters for diagnosing COVID-19 patients." (PMID 38239363, 2023). "To this end, we derived different diversity measures of CCI and used them to study the diversity of CCI in a scRNA-seq dataset of COVID-19 that was sampled from 181 patients across five conditions, focusing in particular on the MIF pathway." (PMID 36105110, 2022). "Focusing on the early phase of ICU treatment, we measured plasma MIF concentrations in COVID-19 patients at day 1 and 3 after ICU enrollment." (PMID 33671433, 2021). "Plasma MIF concentrations were measured in 36 mechanically ventilated COVID-19 patients over three days after intensive care unit (ICU) admission." (PMID 33671433, 2021). "Simultaneously, COVID-19 patients presented high plasma levels of MIF." (PMID 37946732, 2023). "Moreover, the isoform of MIF has been described as an important determinant of COVID-19 symptomatic infection and severity." (PMID 37762413, 2023). "In addition, high concentrations of the macrophage migration inhibitory factor (MIF) were found in serum of COVID-19 patients." (PMID 37946732, 2023). "In order to determine which subpopulations of CD8+ T cells might be responsive to MIF during COVID-19, the expression of CXCR2 and CXCR4 on CD74+ CD8+ T cells was analyzed." (PMID 37946732, 2023). "The interaction between CD74 and MIF may be involved in regulating the inflammatory response in COVID-19 patients, affecting the activation of immune cells and the release of inflammatory mediators." (PMID 37853311, 2023). "We hypothesized that these two pathogenic factors might be related and analyzed the expression of receptors for MIF on T cells in COVID-19." (PMID 37946732, 2023). "Simultaneously, enhanced concentrations of MIF in the serum of COVID-19 patients were observed." (PMID 37946732, 2023). "However, in the severe and convalescence from moderate conditions, the most active multi-receptor unit is the heteromeric complex containing CD74 and CXCR4, indicating differences in the types of MIF-specific interactions across COVID-19 conditions." (PMID 36105110, 2022). "Indeed, it has been shown that MIF levels positively correlate with disease severity in COVID-19, reflecting the inability of patients to control the increased pro-inflammatory cytokine production by anti-inflammatory mechanisms." (PMID 35464430, 2022). "Thus, targeting the dysregulated MIF-CD74 axis might resemble a tractable treatment strategy to interfere with the critical role of MIF in the COVID-19 disease context." (PMID 38992165, 2024). "Thus, enhanced MIF concentrations were associated with the proliferation as well as functionality of bystander CD8+ T cells, and MIF might be an important biomarker of immunopathology in severe COVID-19." (PMID 37946732, 2023). "Hence, T cells in COVID-19 patients express receptors that render them responsive to MIF." (PMID 37946732, 2023). "Thus, augmented MIF signaling might be a regulatory mechanism for the activation of bystander T cells in COVID-19 and may contribute to disease progression and severity." (PMID 37946732, 2023). "It would be interesting to investigate whether MIF, D-DT, and their receptors are also involved in this persistent immune response, and whether they could be potential targets for therapies aimed at mitigating long-term-health COVID-19 consequences." (PMID 37568438, 2023). "In addition, it has been observed that the level of MIF is higher in severe patients with COVID-19." (PMID 35922752, 2022). "Also, MIF can induce lung inflammatory cytokines in the COVID-19-induced inflammatory reaction." (PMID 35733175, 2022). "Being an important inducer of inflammation, MIF may be involved in the pathogenesis of COVID-19." (PMID 35464430, 2022).
COVID-19 (continued). "Therefore, MIF was also identified as a biomarker for determining the patients with COVID-19 ARDS." (PMID 35922752, 2022). "Therefore, we analyzed the plasma concentration of MIF in a cohort study of COVID-19 patients during the ICU stay to evaluate whether circulating MIF plasma concentrations are related to clinically meaningful outcomes during ICU treatment." (PMID 33671433, 2021). "The identified association between an early MIF response, aggravation of organ function and 28-day survival may open future perspectives for biomarker-based diagnostic approaches for ICU management of COVID-19 patients." (PMID 33671433, 2021). "Furthermore, hypertension as comorbidity and increasing MIF concentration as an early biomarker could be related to increased mortality in COVID-19 patients in our study." (PMID 33671433, 2021). "The macrophage migration inhibitory factor (MIF) pathway predicts the outcome of acute respiratory distress syndrome (ARDS) and hallmarks severe COVID-19." (PMID 38195165, 2024). "In particular, a relationship between COVID-19 aggravation and rs10754558 NLRP3, rs6509365 CARD8, rs2043211 CARD8, rs16944 IL1B, and rs755622 MIF have been described." (PMID 38612539, 2024). "In this study, matrix metalloproteinase MMP-3 and microenvironment remodeling factors including MCP-3, MIF, IL-8, SDF-1, and SCYB16 were detected as highly expressed cytokines in COVID-19." (PMID 38476443, 2024). "The study demonstrated that serum levels of MIP-1α, RANTES, Eotaxin, CTACK, GRO-α, IP-10, MIG, basic-FGF, HGF, SCGF-β, G-CSF, M-CSF, SCF, MIF, LIF, and TRAIL were significant higher in COVID-19 patients than in the control group." (PMID 38239363, 2023). "Network pharmacology analyses identified 6 potential targets (IL6, DPP4, MIF, PRF1, SERPING1, and SLC6A4) for emetine in anti-LUAD/COVID-19." (PMID 35733175, 2022). "However, hypertension could not be proven to be an independent risk factor for the development of a severe progression of COVID-19 yet, and also MIF was not described as an independent biomarker for ARDS and, respectively, severe COVID-19 infection." (PMID 33671433, 2021). "Regarding COVID-19 worsening, it seems that ATG16L and MIF polymorphisms do not play a role since our study showed that patients with different disease severity presented similar genetic distribution." (PMID 38612539, 2024). "Lastly, both classical and non-classical monocytes from recovering COVID-19 patients showed higher MIF expression levels." (PMID 37568438, 2023). "Thus, our data confirm the enhancement of MIF upon SARS-CoV-2 infection and also show elevated sCD74 plasma levels in COVID-19 patients." (PMID 37946732, 2023). "Additionally, MIF, along with biomarkers such as D-dimer, troponin, ferritin, and lactate dehydrogenase, predicted ICU admission of COVID-19 patients." (PMID 37568438, 2023). "We found that MIF was DEG and CD74 was both DDG and ‘dark’ gene, which indicated that the combination of DEGs and DDGs could be better used to study COVID-19 in depth." (PMID 37853311, 2023). "In addition, we evaluated the potential bindings of emetine with the LUAD/COVID-19 targets (SLC6A4, MIF, DPP4, PRF1, SERPING1, and IL6)." (PMID 35733175, 2022). "We have found fifteen cytokines that remain upregulated in convalescent COVID-19 individuals one month after infection (IL-1α, IL-3, IL-10, IL-12p70, CCL7, IFN-α2, bFGF, LIF, TRAIL, IL-2, IL-4, IL-5, IL-12p40, IL-17 and MIF) indicating a strong activation of the immune response." (PMID 34681885, 2021). "Overall, levels of MIF were significantly increased in COVID-19 patients in comparison to age- and sex-matched healthy controls, while disease severity did not have an effect on MIF concentrations (mean MIF concentrations: healthy 2.41 ng/ml; mild 8.04 ng/ml and severe 4.44 ng/ml)." (PMID 37946732, 2023).
COVID-19 (continued). "It is also interesting to note that in the transcriptomic studies, the significantly reduced expression of the MIF co-receptor CXCR4 paralleled that of CD74, suggesting that a common mechanism of downregulated expression could occur during moderate and severe cases of COVID-19." (PMID 37568438, 2023). "Therefore, MIF and CD74 might become targets for COVID-19 treatment." (PMID 37853311, 2023). "The significant reduction of PDGF-BB, RANTES, and MIF, in the CAM patients led us to explore the phagocytic activity in the circulating monocytes from the recruited COVID-19 patients, with or without mucormycosis, compared to those from healthy volunteers." (PMID 37052373, 2023). "Our data strongly support this finding in septic patients, now also for critically ill COVID-19 patients, suffering from ARDS, as we could measure significantly higher MIF concentrations in the non-survivors when compared to the survivors." (PMID 33671433, 2021).
liver fibrosis (26 papers, 2014 to 2025). "High macrophage migration inhibitory factor (MIF) levels within exosomes of PaCa origin can induce upregulation of secreted factors through exosomal integrin αVβ5: TGFβ is associated with liver fibrosis." (PMID 35033111, 2022). "In addition to the severity of HCV-induced liver fibrosis and cirrhosis, we evaluated the impact of the MIF promoter polymorphisms on the prevalence of HCC in patients with HCV-induced liver disease." (PMID 31370326, 2019). "VA suppresses liver fibrosis by suppressing autophagy in hepatic stellate cells through inhibition of the MIF/CD74 axis." (PMID 40722864, 2025). "Our results indicate that in TAA-induced liver fibrosis, MIF plays a key mediating role in cardiotoxicity by promoting oxidative stress, inflammation, and fibrogenesis." (PMID 41020850, 2025). "On the other hand, betaine has the ability to exert not only antioxidant but also anti inflammatory and antifibrogenic effects in the myocardium either directly or via modulation of MIF activity in the coexistence of liver fibrosis." (PMID 41020850, 2025). "The study showed that betaine modulates the antifibrogenic effects of MIF in TAA-induced liver fibrosis, by decreasing TGF-β1, PDGF-BB, MMP-2, MMP-9, TIMP-1, and the deposition of ECM (Coll1 and Coll3) in the liver." (PMID 38927544, 2024). "The progression of NAFLD to liver fibrosis can be alleviated by vanillic acid, which inhibits the autophagy of HSCs through the MIF/CD74 signaling pathway." (PMID 39175576, 2024). "The well-known cytokine macrophage migration inhibitory factor (MIF) causes inflammation and modifies liver fibrosis." (PMID 37405480, 2023). "After identifying hepatocytes as a major source of MIF during MCD-induced NASH in mice, we aimed to assess if hepatocyte-derived MIF is also a major functional contributor to liver fibrosis progression." (PMID 33525493, 2021). "The beneficial effects of MIF have been reported in diseases such as community-acquired pneumonia, experimental liver fibrosis, and ischemic heart." (PMID 33610191, 2021). "In a mouse model of toxic liver fibrosis, we showed that MIF exhibits hepatoprotective effects attenuating fibrogenesis by directly interfering with the activation of hepatic stellate cells via the CD74/AMPK signaling pathway." (PMID 31370326, 2019). "The aim of this study was to investigate a correlation between these MIF promoter polymorphisms and the severity of hepatitis C virus (HCV)-induced liver fibrosis." (PMID 31370326, 2019). "Barnes and co-workers studied effects of MIF in chemically induced liver fibrosis (male and female, 10–12 weeks old, C57BL/6 Mif−/− mice)." (PMID 26124760, 2015). "In murine models of fibrosis, MIF was anti-fibrotic; animals deficient for MIF or CD74 had higher risk for hepatic fibrosis." (PMID 24551192, 2014). "However, MIF was a protective factor for high-fat diet-induced liver injury and chemically induced liver fibrosis." (PMID 39851524, 2025). "Additionally, vanillic acid alleviates liver fibrosis by inhibiting autophagy in HSCs via the Macrophage Migration Inhibitory Factor (MIF)/Cluster of differentiation 74 (CD74) signaling pathway." (PMID 41154556, 2025). "Furthermore, we have shown for the first time that MIF exhibits antifibrogenic activity in TAA-induced liver fibrosis and that betaine modulates this antifibrogenic effect of MIF." (PMID 41020850, 2025). "In the liver, MIF stimulated AMPK counteracts the development of liver fibrosis." (PMID 37935315, 2024). "Overall, the dual nature of MIF highlights its involvement in the progression of liver fibrosis." (PMID 38927544, 2024). "This study found dramatically higher levels of D-DT in livers of mice exposed to CCl4, suggesting D-DT may also have an important role in toxin-induced liver fibrosis in addition to MIF." (PMID 35091838, 2022).